CXCL8 (C-X-C motif chemokine ligand 8)
Diseases named in the same sentence as CXCL8 in open-access papers (continued):
Sharing a sentence is not in itself a finding about the gene and the disease.
anaplastic thyroid cancer (4 papers, 2015 to 2024). "Additional evidences supporting the beneficial effects of lowering CXCL8 were provided also in anaplastic thyroid cancer cells." (PMID 29977225, 2018). "The reduction of CXCL8 (and CCL2) was paralleled by impaired tumor angiogenesis and decreased macrophage density both in the in vitro and in vivo models of mice anaplastic thyroid cancer xenograft." (PMID 29977225, 2018).
atrial fibrillation (4 papers, 2018 to 2025). A disorder characterized by an electrocardiographic finding of a supraventricular arrhythmia characterized by the replacement of consistent P waves by rapid oscillations or fibrillatory waves that vary in size, shape and timing and are accompanied by an irregular ventricular response. "Elevated levels of CXCL8, CCL11, CCL2, CXCL10, IL-1β, IL-6, TNF-α, IFN-γ, IL-17, IL-1Ra, IL-4, IL-9, FGF-basic, PDGF, G-CSF, and GM-CSF were observed in the Atrial fibrillation patient, in contrast to uninfected controls." (PMID 29370812, 2018).
bone metastasis (4 papers, 2017 to 2024). Transfer of a neoplasm from its primary site to bones. "Cells of the PC-3 line (isolated from bone metastasis) mainly produce CXCL8/IL-8, while cells of the DU 145 line (isolated from brain metastasis) mainly produce CXCL1." (PMID 37108425, 2023). "Additionally, EP4 antagonists can suppress proinflammatory cytokines (e.g., C-C motif chemokine ligand 2 [CCL2], IL-6, and C-X-C chemokine motif 8 [CXCL8]), reduce inflammation-dependent bone metastasis, and diminish immunosuppression, while restoring antitumor immunity (91, –93)." (PMID 34607951, 2021).
brucellosis (4 papers, 2024 to 2025). Brucellosis is a bacterial infection that spreads from animals to people via unpasteurized dairy products or by exposure to contaminated animal products or infected animals. "As the major contributor of potential inflammatory storm, many inflammatory response genes (e.g., ITGB2, OSM, FPR1, CEBPB, NINJ1) and canonical pro‐inflammatory cytokines (e.g., CXCL8, CCL3, CCL4, TNF, IL1B, S100A12) were expressed at higher levels in brucellosis patients than in healthy donors." (PMID 39135683, 2024). "Additionally, we also detected high expression of typical inflammatory cytokines (e.g., S100A8/9/12, IL1B, IL6, CXCL8, CCL2, CXCL10) in brucellosis patients during the acute phase." (PMID 39135683, 2024). "Procarta cytokine analysis from the plasma of these individuals, supported the finding that brucellosis patients, especially for acute patients, had a higher level of multiple pro‐inflammatory cytokines, such as CXCL8/IL8, CCL3/MIP‐α, CCL4/MIP‐β, TNF/TNF‐α, IL1B/IL1‐β." (PMID 39135683, 2024).
Candidemia (4 papers, 2013 to 2021). A form of invasive candidiasis where species of CANDIDA are present in the blood. "Given the large number of circulating platelets, elevated TNF-α and CXCL8 levels may crucially affect the outcome of candidemia." (PMID 34938671, 2021).
Chagas disease (4 papers, 2022 to 2024). A parasitic infection caused by Trypanosoma cruzi. "Regarding chemokines, CXCL10 and CCL5 were increased in IND and CCC patients compared to CTRL, while CCL2, CXCL9 and CXCL8 were reduced in both clinical forms of Chagas disease compared to CTRL." (PMID 38390336, 2024).
Constipation (4 papers, 2021 to 2025). Infrequent or difficult evacuation of feces. "Higher levels of CXCL8 in stool were also associated with constipation-related stool consistency in PD patients and with lower defecation frequency in controls." (PMID 33557896, 2021).
cryptococcal infection (4 papers, 2017 to 2024). "Among the inflammatory cytokines produced from these pathways include CCL3, CXCL8, IL-12, and IL-23 which each contribute to the control of a cryptococcal infection through recruitment of other immune cells or enhancing a Th1 or Th17 adaptive immune response." (PMID 36466930, 2022).
enterocolitis (4 papers, 2017 to 2026). An inflammatory process affecting the small intestine and colon. "Surprisingly, the expression of CXCL8 is significantly enhanced in the larval intestine of TNBS-induced enterocolitis zebrafish models." (PMID 28515725, 2017).
gonococcal infection (4 papers, 2018 to 2024). "In addition to CXCL8 and IL1B, we also observed multiple genes previously shown to be involved in responses to gonococcal infections, including PTGS2 and ICAM1." (PMID 38976720, 2024).
granulomatosis with polyangiitis (4 papers, 2014 to 2025). A small-vessel necrotizing vasculitis characterized by the association of inflammation of the vessel wall and peri- and extravascular granulomatosis. "Proteinase 3 (PR3), which is mainly produced by neutrophils and is the main autoantigen in granulomatosis with polyangiitis, binds also to endothelium and induces CXCL8 (IL-8) and CCL2 (MCP-1) that provide chemotactic signals for neutrophils and monocytes." (PMID 28018358, 2016).
Japanese encephalitis (4 papers, 2012 to 2022). A disease due to a virus transmitted by an arthropod). "High levels of CXCL8 have been reported in several other viral CNS infections including herpes simplex encephalitis, herpes simplex meningitis, and Japanese encephalitis patients." (PMID 30777092, 2019).
Kawasaki disease (4 papers, 2016 to 2025). A rare inflammatory disease characterized by an acute febrile, systemic, self-limiting, medium-vessel vasculitis primarily affecting children. "Our study shows that we can distinguish normal samples from Kawasaki disease samples based on the infiltration of immune cells, and that CXCL8, CCL5, CCR7, CXCR3, and CCR1 may play important roles in the development of Kawasaki disease." (PMID 33188570, 2021).
laryngeal carcinoma (4 papers, 2009 to 2021). Carcinoma that arises from the laryngeal epithelium. "Indeed, anakinra was found to reduce circulating levels of CXCL8, tumour growth and the number of infiltrating TAM into mice bearing erlotinib-resistant adenosquamous OSCC (Cal27) and laryngeal carcinoma (SQ20B) xenografts grown subcutaneously." (PMID 35047989, 2021).
leiomyoma (4 papers, 2014 to 2023). A well-circumscribed benign smooth muscle neoplasm characterized by the presence of spindle cells with cigar-shaped nuclei, interlacing fascicles, and a whorled pattern. "Many proteins such as F3, WNT2, CDH1, and LIF shown in the protein–protein interaction networks are well known in leiomyoma pathogenesis, and others, such as ICAM1, CXCL8, CCL2, and NANOG are novel and require further investigation." (PMID 36835153, 2023).
medullary thyroid carcinoma (4 papers, 2014 to 2018). "More importantly, CXCL8 was identified as a potential biomarker of sunitinib responsiveness, because in vivo the circulating levels of CXCL8 dramatically decreased following sunitinib administration in medullary thyroid cancer xenografts." (PMID 29977225, 2018). "Sunitinib, a multi-kinase inhibitor with both anti-angiogenic and antitumor activities, was demonstrated to strongly reduce CXCL8 secretion in medullary thyroid cancer cells." (PMID 29977225, 2018). "Finally, it has been demonstrated that many types of human carcinomas (breast, colon, cervical, gastric, lung, ovarian, and medullary thyroid carcinoma) express high levels of CXCL8/IL-8 compared to normal tissues." (PMID 26379707, 2015).
Meningococcal disease (4 papers, 2019 to 2025). "Despite strain and donor variability, meningococcal infection universally induced cytokines CCL20, CXCL1, CXCL8, CXCL10, and IL-18, with significantly higher CCL20 levels 24 h post-MenW cc11 infection." (PMID 40586572, 2025). "Upon meningococcal infection, we observed a mostly universal induction of CCL20, CXCL1, CXCL8, CXCL10, and IL-18 secretion 24 h post-infection, regardless of the specific meningococcal strain used for infection." (PMID 40586572, 2025). "Meningococcal disease is hallmarked by elevated concentrations of proinflammatory cytokines and chemokines, including IL-1β, tumor necrosis factor (TNF), IL-6, and CXCL8 (formerly known as IL-8)." (PMID 31198794, 2019).
Opportunistic infection (4 papers, 2014 to 2024). An infection that is caused by a pathogen that would generally not be able to cause an infection in a host with a normal immune system. "The failure to completely suppress CXCL8 gene expression may be important clinically as total suppression of the innate immune response may lead to opportunistic infections." (PMID 24759736, 2014).
Osteopenia (4 papers, 2010 to 2023). Osteopenia is a term to define bone density that is not normal but also not as low as osteoporosis. "This induces the release of TNF and CXCL8 (i.e., IL-8), which promote osteoclast differentiation and activation in an autocrine fashion, leading to osteopenia and bone resorption in vivo." (PMID 36059838, 2022).
Pneumocystis Pneumonia (4 papers, 2010 to 2021). "Significant differences in the median values of IL-1β, TNF-α, IFN-γ, IL-18, IL-17A, IL-33, IL-13, and CXCL8 were reached in all the groups studied, suggesting that these cytokines play a role in the inflammatory processes associated with histoplasmosis and pneumocystosis." (PMID 34829225, 2021). "Significant differences in median values of SP-A, IL-1β, TNF-α, IFN-γ, IL-18, IL-17A, IL-33, IL-13, and CXCL8 were found among all the groups studied, suggesting that these cytokines play a role in the local inflammatory processes of histoplasmosis and pneumocystosis." (PMID 34829225, 2021).
Primary immunodeficiency (4 papers, 2023 to 2025). "the GSEA results showed that CXCL8, IL1B and CCL2 affect Graft-versus-host disease, Legionellosis, Primary immunodeficiency, Primary bile acid biosynthesis, Protein export and Non-homologous end-joining signaling pathways." (PMID 38167125, 2024).
toxoplasmosis (4 papers, 2015 to 2025). A parasitic disease contracted by the ingestion or fetal transmission of toxoplasma gondii. "We then asked if neutrophils could be one of the sources of CXCL8, CCL4, CXCL9, and CXCL10 during toxoplasmosis." (PMID 34607465, 2021).
cerebral aneurysms (3 papers, 2020 to 2024). "Animal studies indicate two chemokines—C-X-C motif chemokine–ligand–8 (CXCL8/IL-8) and monocyte chemoattractant protein-1 (CCL2/MCP-1)—especially important in the formation and rupture of cerebral aneurysms." (PMID 32517149, 2020).
chronic granulomatous disease (3 papers, 2007 to 2015). Chronic granulomatous disease (CGD) is a rare primary immunodeficiency, mainly affecting phagocytes, which is characterized by an increased susceptibility to severe and recurrent bacterial and fungal infections, along with the development of granulomas. "Microarray analysis of blood PMN from patients with X-linked chronic granulomatous disease revealed increased mRNA levels for only two chemokines, namely CXCL8 and CXCL1." (PMID 17875202, 2007).
chronic GVHD (3 papers, 2021 to 2024). "Tear levels of epidermal growth factor and IP-10/CXCL10 are significantly decreased, while tear levels of interleukin-1Ra, IL-8/CXCL8, and IL-10 are significantly increased in patients with ocular chronic GVHD compared to healthy controls under controlled environmental conditions." (PMID 39200870, 2024).
Cryptosporidium infection (3 papers, 2016 to 2023). "Studies in human intestinal ECs show that chemokines such as CCL-5, CXCL-8, and CXCL-10 are upregulated in Cryptosporidium infection, and CXCL-8 is detectable in the stool samples of children infected with cryptosporidiosis." (PMID 37110479, 2023).
food allergy (3 papers, 2020 to 2022). Gastrointestinal disturbances, skin eruptions, or shock due to allergic reactions to allergens in food. "Within these, 113 genes (27.8%) have been previously associated with food allergy; within the top 10 DE genes, 8 genes have been previously linked to food allergy—C3, CXCL8, RARRES1, CXCL6, MUC5AC, CXCL1, and SAA3." (PMID 36452260, 2022).
infectious colitis (3 papers, 2013 to 2020). A viral or bacterial infectious process affecting the large intestine. "Such host–pathogen interaction at the colonic mucosa resulted in the production of the neutrophil chemoattractant CXCL8 (humans)/CXCL1 (mice) and pathogen clearance, representing a novel endogenous innate cathelicidin defense in the setting of infectious colitis." (PMID 32658599, 2020).
neuromyelitis optica (3 papers, 2020 to 2023). A rare inflammatory disease of the central nervous system characterized mainly by attacks of uni- or bilateral optic neuritis (ON) and acute myelitis. "CSF CXCL8 concentration has been studied in MS and other CNS inflammatory disorders showing higher levels in antibody-mediated diseases such as neuromyelitis optica rather than in MS." (PMID 36215027, 2023).
optic neuritis (3 papers, 2017 to 2025). Optic neuritis is inflammation of the optic nerve, the nerve that carries the visual signal from the eye to the brain.The conditionmay cause sudden, reduced vision in the affected eye(s). "Furthermore, concentrations of CXCL8, CXCL10 and CCL20 in sera did not significantly differ among subgroups of MS patients divided by presence or localization of demyelinating lesions (supratentorial, infratentorial and cervical), sex, or history of optic neuritis." (PMID 39125633, 2024).
papilloma (3 papers, 2006 to 2021). A benign epithelial neoplasm that projects above the surrounding epithelial surface and consists of villous or arborescent outgrowths of fibrovascular stroma. "We observed the expression of angiogenic chemokines such as CXCL8 (IL-8) and VEGF within papillomas, consistent with previous findings." (PMID 34931021, 2021).
pituitary tumour (3 papers, 2019 to 2023). "Chemokines, such as CXCL8 (or interleukin (IL)-8), CCL2, CCL3, and CCL4, are secreted by pituitary tumors and non-tumor cells, such as macrophages, lymphocytes, or fibroblasts, and modulate the microenvironment composition." (PMID 37958702, 2023).
primary ciliary dyskinesia (3 papers, 2017 to 2026). A rare, genetically heterogeneous, primarily respiratory disorder characterized by chronic upper and lower respiratory tract disease. "The airways of patients with primary ciliary dyskinesia (PCD) contain persistently elevated neutrophil numbers and CXCL8 levels." (PMID 34201048, 2021). "The non-normalized CXCL8 and IL-1β levels released by peripheral blood mononuclear cells (PBMCs) from adult controls (Ad CO), pediatric controls (Ped CO) and patients with primary ciliary dyskinesia (PCD)." (PMID 29018439, 2017).
pustular psoriasis (3 papers, 2024 to 2025). "Another genetic defect associated with pustular psoriasis is the IL36RN mutation, which decreases activity of the IL-36R antagonist and increases IL-36R signaling, leading to expression of IL-1β and CXCL8." (PMID 38448036, 2024). "Furthermore, skin explants of pustular psoriasis cultured with a neutralizing anti-IL-26 mAb but not anti-IL-17A mAb completely inhibited the expression of CXCL1, CXCL8, and IL1A, confirming the specific role of IL-26 as a driver of pathogenic autoinflammation circuits." (PMID 38448036, 2024).
rectum adenocarcinoma (3 papers, 2021 to 2024). An adenocarcinoma arising from the rectum. "Moreover, a significant association was observed between the CXCL8/9/10/11 expression and immune infiltration in colonic and rectal adenocarcinoma." (PMID 34233297, 2021). "In rectum adenocarcinoma, CXCL1 and CXCL3 negatively correlated with EMT, while CXCL5, CXCL6, PPBP, and CXCL8 were positively correlated." (PMID 37686093, 2023).
Respiratory tract infection (3 papers, 2020 to 2021). An infection of the upper or lower respiratory tract. "CXCL8 plays a major role in the initial control of respiratory tract infection due to its chemotactic activity for neutrophils and monocytes." (PMID 33726831, 2021).
ST Elevation Myocardial Infarction (3 papers, 2014 to 2020). A myocardial infarction that produces elevation in the ST segments of the ECG. "Recently, high levels of CXCL8 in patients suffering ST elevation myocardial infarction, complicated by HF, were associated with less improvement in LV function during the first 6 weeks after PCI, suggesting a possible role of CXCL8 in the reperfusion-related injury." (PMID 27242392, 2016).
streptococcal infection (3 papers, 2022 to 2023). Any of the several infectious disorders caused by members of streptococcus, a genus of gram positive bacteria belonging to the family Streptococcaceae. "Potential SpyCEP antagonists modelled on CXCL8 but with reduced CXCR1 and CXCR2 activity have previously been described and could in theory provide adjuvant therapies for more severe invasive streptococcal infections that fail to respond to antibacterial agents alone." (PMID 34649250, 2022).
synovial sarcoma (3 papers, 2020 to 2025). "Among upregulated cytokine genes Cxcl15 which encodes for IL-8, the mouse homolog of human CXCL8/IL-8, was upregulated both in mouse and human miR-214-overexpressing synovial sarcoma." (PMID 32019274, 2020). "The mouse Cxcl15/Il8, a counterpart of human CXCL8/IL8, was upregulated in both human synovial sarcoma and mouse synovial sarcoma with miR-214 expression." (PMID 32019274, 2020).
tongue cancer (3 papers, 2014 to 2025). A malignant neoplasm affecting the tongue. "The two ligands for CXCR1, CXCL6 and CXCL8, which also activate CXCR2, are both up-regulated, indicating that a shift towards activation of CXCR2 could be of importance for tongue carcinoma." (PMID 24395654, 2014).
uterine cancer (3 papers, 2008 to 2024). Primary or metastatic malignant neoplasm involving the uterine corpus and/or the cervix. "Notably, analysis of TCGA Pan-Cancer Atlas showed a consistent positive correlation between SERPINB3 and CXCL1, CXCL8, S100A8, and S100A9 across multiple tumor types including bladder, breast, head and neck, lung, prostate, and uterine cancers." (PMID 37279067, 2023).
Acute otitis media (2 papers, 2021 to 2024). Acute otitis media is a short and generally painful infection of the middle ear. "In children, elevated cytokine levels of CXCL8 and TNF have been associated with positive cultures for S. pneumoniae in NP during acute otitis media." (PMID 38271409, 2024).
ANCA-associated vasculitis (2 papers, 2017 to 2024). "Yokoseki also reported increased levels of IL-6, C-X-C motif ligand (CXCL)-8, and CXCL-10/IFN-γ inducible protein (IP)-10 in cerebrospinal fluid of HP with ANCA-associated vasculitis or IgG4-RD." (PMID 38988571, 2024).
arbovirus infection (2 papers, 2021 to 2025). A viral infection that is transmitted by an arthropod. "This included a crucial set of genes that have been implicated in increased susceptibility to arbovirus infection, including neutrophil-attracting chemokines (CXCL1, CXCL3, CXCL8)." (PMID 41150413, 2025).
astrocytic neoplasms (2 papers, 2012 to 2020). "It is interesting to note that AEG-1 expression in astrogliomas has been shown to induce CXCL8 expression and matrix metalloproteinase-9 production, both of which show a dramatic increase during gliosis." (PMID 22884085, 2012). "Moreover, it was demonstrated that there is a strong positive correlation between level of CXCL8 and the number of macrophages in astrocytic neoplasms." (PMID 32456359, 2020). "Moreover, CXCL8 was detected in the cyst fluid of primary astrocytic tumors." (PMID 32456359, 2020).
autoimmune hypothyroidism (2 papers, 2023). "The genotype frequency of CCL11(rs3744508)AA(OR = 11.3) was higher in Hashimoto's thyroiditis (HT) patients, whereas that of CXCL8(rs2227306)CC(OR = 0.4) was lower in HT patients." (PMID 37730733, 2023).
colon adenoma (2 papers, 2014 to 2015). An adenoma that arises from the colon. "CXCL8/IL-8 specifically colocalizes with arrested p16INK4A-positive epithelium in human colon adenomas." (PMID 24966464, 2014).
colonic disease (2 papers, 2011 to 2022). "This study suggests that inhibiting CXCL8/CXCR2 should be investigated in patients with right‐sided colonic disease and stroma‐rich tumours." (PMID 35879507, 2022).